BRAF (B-Raf proto-oncogene, serine/threonine kinase)
Diseases named in the same sentence as BRAF in open-access papers (continued):
Sharing a sentence is not in itself a finding about the gene and the disease.
melanoma (continued). "Using DISCOVER analysis we identified eight statistically significant mutually exclusive genetic interactions, six with BRAF and two with CDKN2A, each representing important insights into the pathways through which melanoma develops." (PMID 36219477, 2023). "Deregulation of two major signalling pathways, the RAS-RAF-MEK-ERK and PI3K-AKT-PTEN, are key drivers of melanoma development and progression, with ~50% and ~25% of patients expressing constitutively active mutants of MAP-kinases BRAF and NRAS, respectively." (PMID 37495601, 2023). "In melanoma, HDAC8 mediates the escape from BRAF inhibitor therapy, and HDAC8 and BRAF dual inhibition has been suggested as a potential therapeutic strategy for melanoma treatment." (PMID 36831463, 2023). "We also observed a decrease in BRAF RNA levels and protein expression upon MALAT1 inhibition in melanoma." (PMID 37235843, 2023). "Targeted therapies, such as BRAF (BRAFi) and MEK (MEKi) inhibitors, represent one of the most significant advances in the treatment of BRAFV600E melanomas." (PMID 37183363, 2023). "Encorafenib combined with binimetinib was well tolerated in a phase III trial showing potent antitumor activity in BRAF-mutant melanoma, making a rapid evaluation in NRAS-mutant melanoma imminently feasible." (PMID 38067230, 2023). "Ongoing studies include the Columbus-AD study (NCT05270044) evaluating the efficacy and safety of 12 months of BRAF (encorafenib) and MEK (binimetinib) inhibitors versus placebo in resected stage IIA/B/C melanoma patients." (PMID 37888038, 2023). "Mutations of the oncogenes v-raf murine sarcoma viral oncogene homolog B1 (BRAF) and neuroblastoma RAS viral oncogene homolog (NRAS) are the most frequent genetic alterations in melanoma and are mutually exclusive." (PMID 36982192, 2023). "Age, BRAF status, categorical LDH group, ECOG performance status, metastatic stage, melanoma subtype, and line of therapy all were retained in the model at p<0.15 in both analyses, with and without adjustment for classifier prediction." (PMID 37388743, 2023). "As for the observed effect of the combination therapy, BRAF and MEK inhibitors have shown significant improvements in clinical outcomes in BRAFV600E-mutant melanoma, non-small-cell lung cancer, and ATC." (PMID 36624452, 2023). "Deletion of negative ERK regulators, including DUSP4, DUSP6, and PEA15, induced cell death in BRAF and NRAS mutant melanomas due to unrestrained activation of ERK." (PMID 37803324, 2023). "Meanwhile, the systematic strategy of combining BRAF/MEK inhibitors with radiotherapy and immunotherapy also brought hope to patients with melanoma MBM." (PMID 38104104, 2023). "In melanoma 25, TSLNC8 overexpression diminished tumor growth rate and weight and enhanced the cytotoxic effects of the BRAF inhibitor PLX4720." (PMID 37781073, 2023). "In 2013, dabrafenib, another BRAF inhibitor, and trametinib, an MEK inhibitor, were approved for melanoma treatment based on the BREAK-3 and METRIC trials, respectively." (PMID 37504268, 2023). "For instance, pan-RAF inhibitor LXH254 blocks dimeric BRAF and CRAF, which can provide a potential clinical strategy when combined with MEK or ERK inhibitors to treat KRAS mutant NSCLC or NRAS mutant melanoma." (PMID 38111008, 2023). "While in a randomized study of advanced melanoma patients treated with T-VEC, patients with mutant BRAF occurred CR in 5 (10.9%) and PR in 9 (19.6%) patients, and patients with wild-type BRAF occurred CR in 5 (11.1%) and PR in 9 (20.0%) patients." (PMID 37919738, 2023). "Subsequently, adjuvant BRAF/MEK-inhibition therapy was approved and reimbursed for the treatment of resected stage III melanoma patients in the Netherlands in November 2020." (PMID 36672358, 2023). "When we inhibited both BRAF and PLK1, we achieved an improved response of BRAFi-resistant melanoma cells, which was comparable to the combined inhibition of BRAF and EZH2." (PMID 36768289, 2023).
melanoma (continued). "Targeted therapies, including BRAF and MEK inhibitors, have shown promise in the treatment of melanoma." (PMID 37515699, 2023). "In melanoma, RNF43 has been found to inhibit cell invasion and reverse the resistance to BRAF V600E and MEK inhibitors by stimulating the ubiquitination and proteasomal degradation of VANGL2 and inhibiting ROR2 in vitro and in vivo." (PMID 37848933, 2023). "In melanoma, the reactivation of the MAPK pathway during BRAF/MEK blockade can occur through several mechanisms, including amplification of the BRAF gene." (PMID 36901733, 2023). "We present two cases of BRAF and MEK inhibitor-related sarcoidosis in patients with melanoma and review the literature." (PMID 37706179, 2023). "In melanoma, one of the melanoma survival oncogenes, MITF, is found to be the driver for the reversible DT state after exposure to BRAF and MEK inhibitors." (PMID 37638338, 2023). "BRAF- and MEK-inhibitors are highly effective targeted drugs in melanoma therapy, but they can induce drug resistance both in vitro and in patients." (PMID 36674794, 2023). "Such alterations induce in melanoma cells an activation of the integrin β1/FAK/Src pathway, which in turn activates the ERK pathway signaling and consequently leads to a resistance to BRAF inhibition." (PMID 37174072, 2023). "In another phase II, open-label, multicentre study of T-VEC in patients with stage IIIB-IVM1c melanoma, the ORR of mutant BRAF was 10 (25%) patients, and that of wild-type BRAF was 20 (29%) patients." (PMID 37919738, 2023). "SMAD3 plays a key role in melanoma resistance to treatment by promoting an EMT-like process, and their results suggest that the regulation of BRAF inhibitor resistance gene expression is multiparametric." (PMID 38084101, 2023). "BRAF/MEK inhibitors and anti-PD-1 therapy risks and benefits should be assessed when considering first-line treatment in adjuvant melanoma patients." (PMID 36672358, 2023). "These agents bind to BRAF and MEK, which are vital components of the MAPK signalling pathway, making them critical treatment strategies for patients with BRAF-mutant melanoma." (PMID 37887294, 2023). "Combined BRAF and MEK inhibition addresses this MAPK-mediated mechanism of resistance and constitutes the current standard-of-care for targeted melanoma therapy." (PMID 37993971, 2023). "We recognize that incorporating the BRAF status could provide valuable information to other clinicians and researchers, enabling them to understand the genetic characteristics of this rare presentation and contributing to the advancement of personalized medicine for melanoma patients." (PMID 38104134, 2023). "Hence, with the BRAF V600E mutation, CMN can have more proliferative activity and maybe more susceptible to other irritant factors, such as sun exposure and friction, and would eventually progress to malignant melanoma." (PMID 37156689, 2023). "BRAF, RAS and NF1 proteins are involved in the MAPK signalling pathway, which is often deregulated in melanoma, resulting in stimulation of cell proliferation and survival." (PMID 36765773, 2023). "Inhibition of the BRAF/MEK pathway leads to apoptosis, and the suppression of cell proliferation and metastasis in melanoma cells." (PMID 36678596, 2023). "Currently, for both BRAF-mutant and BRAF-wild-type melanoma, ICI combination therapy has become the preferred first-line therapy for metastatic and recurrent melanoma." (PMID 36647169, 2023). "The non-BRAF-mutant WM3406 and MeWo cells were treated with cobi alone, since the BRAFi would be ineffective in these melanoma subtypes." (PMID 37616051, 2023). "Novel Precision Medicine therapies, such as BRAF V600E inhibitors in patients with melanoma and PD1/PD-L1 immunotherapy for melanoma, lung, kidney, and other types of cancer, are enabling more efficient treatment with minimized side effects." (PMID 37107559, 2023).
melanoma (continued). "Studies with KRAS inhibitors mirror earlier work, which demonstrated the ability of BRAF and MEK inhibitors to enhance the therapeutic activity of ICB in LUAD, colorectal cancer, and melanoma mouse models." (PMID 37581538, 2023). "HBL cells belong to the triple-WT molecular subtype of melanomas (NRAS, BRAF and NF1 WT) and they respond to stimulation with melanocortin agonists with strong increases in both cAMP and ERK1 and ERK2 activity." (PMID 37762683, 2023). "The loss of SOX10 led to the development of an invasive, slow-cycling state in melanoma cells, promoting tolerance to BRAF and/or MEK inhibitors, which are commonly used in melanoma treatment." (PMID 38132479, 2023). "Combination therapy using both BRAF and MEK inhibitors can improve overall survival for patients with BRAF-mutant melanoma." (PMID 36856908, 2023). "As concerning MAPK pathways, their activation, via Ras-BRAF-MEK-ERK, represents an important step in melanoma, driving enhanced cell proliferation, inhibition of apoptosis, invasion, and metastasis." (PMID 36902392, 2023). "Resistance mechanisms to BRAF and MEK inhibition beyond melanoma have been reported in lung and thyroid cancer however, this has been infrequently described in gliomas." (PMID 37231247, 2023). "In contrast, RFS was significantly worse for patients with TMB-high and BRAF wild type and even more for those with TMB-low and BRAF wild type melanomas." (PMID 35192052, 2023). "Targeting oncogenic BRAF makes melanoma more immunogenic and promotes a more favorable TME by normalizing tumor vasculature, enhancing melanoma antigen presentation, and inducing cytotoxic CD8+ cells infiltration." (PMID 37183363, 2023). "Collectively, these results demonstrate that the combination of BRAF and PI3K inhibitors effectively reduced vemurafenib‐induced fibroblast activation and exhibited notable efficacy in suppressing melanoma invasion and proliferation." (PMID 36026581, 2022). "The resistance of our MEK1 Q56P melanoma model to both MEK and BRAF inhibitors confirms the prior discovery of BRAF inhibitor cross-resistance with stable expression of exogenous MEK1 Q56 and MEK1 P124 mutant alleles in A375 cells." (PMID 36358868, 2022). "Therefore, melanomas may be molecularly classified into four major genetic subtypes: BRAF-mutated, RAS-mutated, NF1-mutated and, if none of the three previous genes are mutated, triple-wildtype." (PMID 36143375, 2022). "Previous studies have focused on inhibiting this signaling pathway by blocking the activity of BRAF and MEK, and drugs targeting these pathways have achieved remarkable efficacy in the treatment of melanoma." (PMID 36077604, 2022). "The MITF transcription factor directly binds to the kinase domain of RAF kinases, including ARAF, BRAF and CRAF in melanoma cells." (PMID 35091687, 2022). "It was shown that a combination of BRAF and MEK inhibitors treatment triggered the pyroptosis of human melanoma cells through inducing caspase-3 activation and GSDME cleavage." (PMID 35896522, 2022). "In line with this notion, we found that DNA amplification and elevated mRNA levels of DDR1 negatively correlated to the activity of BRAF and MEK inhibitors in melanoma cell lines from the GDSC (Genomic of Drug Sensitivity in Cancer)." (PMID 34957688, 2022). "As such, BRAF/MEK inhibitor therapy may not be the best option as first-line in the metastatic setting but should be considered in the adjuvant setting for BRAF-mutated IIIA-B melanoma." (PMID 36058945, 2022).
melanoma (continued). "Regarding EGFR-mediated control of tensile Rac1 activity, ERK/MAPK signalling has been implicated to drive the overexpression and activation of the Rac-GEF in BRAF- and NRAS-mutant melanoma, as well as in KRAS- and EGFR- mutant lung cancer." (PMID 36224221, 2022). "Currently, BRAF inhibitor vemurafenib and MEK inhibitor trametinib are the most common drugs used for the treatment of melanoma." (PMID 36686679, 2022). "The combination of BRAF and MEK inhibitors has been widely used to treat BRAF-mutant melanoma patients, achieving satisfactory results." (PMID 36125617, 2022). "This preclinical evidence that both BRAF and MEK inhibitors can enhance the immune recognition of melanoma cells provides a strong rationale for the combination of immunotherapy and targeted therapy in advanced melanoma." (PMID 36428582, 2022). "Adjuvant combination BRAF and MEK inhibition is an approved treatment for resected stage III melanoma but requires diligent toxicity assessment and management." (PMID 36212431, 2022). "In fact, at variance with what was observed for melanoma, vemurafenib - the first specific BRAFV600E inhibitor tested - showed modest clinical activity in mCRC patients with BRAF-mut tumors." (PMID 35582524, 2022). "AHF used the following search terms: 'BRAF,' 'BRAFV600', 'molecular testing,' 'melanoma,' and 'colorectal cancer' in combination with 'Latin America' from January 1, 2016 to January 10, 2022." (PMID 36589179, 2022). "Combination therapy of BRAF V600E inhibitor with MEK or EGFR inhibitors enhances the efficacy compared to monotherapy and prolongs the overall survival of CRC and melanoma patients 55-58." (PMID 35966590, 2022). "In melanoma, SNVs in NF1 were more frequent in tumours of older individuals, while BRAF SNVs were more frequent in tumours of younger individuals." (PMID 35017538, 2022). "Compared with the BRAF inhibitor alone, the combined treatment of BRAF and MEK inhibitors has shown a better effect for melanoma patients." (PMID 36551302, 2022). "Consistent with the in vitro data, co-targeting BRAF and HDAC8 showed synergistic anti-tumor effects in melanoma mouse models." (PMID 36231123, 2022). "On the one hand, in vivo and clinical evidence support that targeting mutant BRAF increases antigen expression, MHCs class I and II and PDL1 expression in melanoma cells as well as an increase in CD8+ T-cell infiltrate in tumors of patients." (PMID 36358912, 2022). "In the purpose, combined BRAF and MEK inhibition have significantly improved overall survival in melanoma patients." (PMID 35327519, 2022). "Around 90% of melanomas express abnormal activation of the MAPK pathway, providing a strong rationale for clinical use of BRAF and MEK inhibitors." (PMID 36084109, 2022). "To date, the targeted therapy for NRAS-mutant melanoma is based on MEK inhibitors, unfortunately with efficacy lower than that designed for BRAF-mutant melanoma." (PMID 36400750, 2022). "We tested these combinations in two BRAFV600E-mutant melanoma cell lines, UCSD354L and A375-R1, which possess intrinsic and acquired resistance respectively to BRAF/MEK inhibition." (PMID 35193687, 2022). "We also recently demonstrated that stiff and aligned collagen and fibronectin rich matrices deposited by MAFs protected melanoma cells from BRAF/MEK inhibitor treatment, when melanoma cells were cultured on top of these matrices." (PMID 36119516, 2022). "In primary melanoma patient samples, TBK1 is hyperactive in a subtype of BRAF/MEK inhibitor-resistant tumor cells; this subtype of melanoma displays hyperactive TLR/innate immune system signaling." (PMID 35395857, 2022). "The limited treatment of choice for advanced melanoma is immune checkpoint blockade (ICB) and molecularly targeted therapies, such as CTLA-4, PD-1/PD-L1 inhibitors, and BRAF inhibitors due to melanoma's high level of heterogeneity and aggressiveness." (PMID 36467505, 2022).
melanoma (continued). "Currently, the combination of BRAF and MEK inhibitors is a standard of care for the treatment of melanoma in advanced disease as well as adjuvant settings." (PMID 35159044, 2022). "This reduction suggests a decrease of the glycolytic metabolism in the YUMM1.7 melanoma xenografts in response to single BRAF or MEK inhibition, as well as in response to the combined BRAF and MEK inhibition." (PMID 35327519, 2022). "BRAF and NRAS cooperate with Rho-ROCK for transformation, and as such BRAF- and NRAS-mutant melanomas harbour amoeboid characteristics." (PMID 36699013, 2022). "A screen identified SMARCB1 as a factor required for mutant BRAF-induced senescence, suggesting a tumor suppressor role for SMARCB1 in melanomas that harbor this oncogene." (PMID 35323214, 2022). "In melanoma patients, one of the most immunogenic cancers, immune checkpoint inhibitors (ICI) and MAPK-targeted therapy—BRAF/MEK inhibitors—have revolutionized prognosis, and the study of the microbiome as a modulating factor is thus appealing." (PMID 36233289, 2022). "More recently targeted inhibitors, especially those against BRAF and MEK inhibitors, have emerged as important therapeutic agents in melanoma therapy." (PMID 35626272, 2022). "We and others have recently shed new light on the immunomodulatory effects of CDK4/6i, both alone and in combination with current melanoma standard-of-care therapies, including ICI (targeting PD-1, PD-L1, and CTLA-4) and targeted BRAF and MEK therapies." (PMID 35444175, 2022). "In melanoma, ACOX1-mediated fatty acid oxidation is involved in tumor resistance to BRAF/MEK inhibitors." (PMID 36177002, 2022). "Inhibition of BRAF and MEK are among the most successful current treatment strategies for fighting melanoma." (PMID 35559262, 2022). "Several clinical trials have shown the antitumour effects of BRAF inhibitors alone or in combination with BRAF and MEK inhibitors against BRAF‐mutant melanoma." (PMID 35332658, 2022). "In melanoma, a recent study showed the existence of a positive STAT3-SOX2-CD24-STAT3 regulatory loop that is induced upon BRAF inhibition and sustains adaptive response to BRAFi." (PMID 35944584, 2022). "Recent studies suggest that inhibition of BRAF and MEK, combined with anti-PD-1/L1 antibodies, improves prognosis of melanoma patients in a CD8 T cell dependent mechanism." (PMID 35954441, 2022). "The combination of BIX-01294 with BRAF and MEK inhibitors exhibited a high level of synergistic effects in killing melanoma cells and even resistant cells." (PMID 36582533, 2022). "BRAF-mutant melanomas are prevalent in body areas of intermittent sun exposure, while NRAS-mutant melanomas are mainly observed in chronic sun-damaged areas." (PMID 35804995, 2022). "Treatment with BRAF and MEK inhibitors in melanoma is characterized by the development of resistance related to the onset of secondary mutations." (PMID 35053435, 2022). "Melanoma cells with BRAFV600E or wild type BRAF showed a reduction in tumour cell proliferation in vitro and tumour growth in xenograft models when using shRNA against ERK5, suggesting that ERK5 therapies could have benefit in tumours carrying either wild type BRAF or BRAFV600E mutations." (PMID 35903549, 2022). "BRAF-mutant melanoma cells with increased expression of EGFR are less sensitive to BRAF inhibitors and elevated expression of EGFR together with NGFR characterizes pre-resistant melanoma cells, which are selected during therapy and lead to treatment failure." (PMID 35565444, 2022). "BRAF, a serine/threonine kinase in the MAPK signaling pathway, was first reported in 46-66% of melanomas." (PMID 35712493, 2022). "Combined treatments with BRAF and MEK inhibitors have improved the prognosis of melanoma patients compared to monotherapy with BRAF inhibitors alone." (PMID 35335966, 2022).